APOE (apolipoprotein E)
Diseases named in the same sentence as APOE in open-access papers (continued):
Sharing a sentence is not in itself a finding about the gene and the disease.
Alzheimer disease (continued). "In studies of the elderly, the main effects of APOE genotypes (regardless of sex) as well as the effects of interaction between sex and APOE genotypes on the risk of Alzheimer’s disease, cognitive functions, and neural mechanisms were explored." (PMID 32954402, 2021). "However, some carriers of ApoE E4 variation haven’t developed an Alzheimer’s disease so it is very likely that other genetic factors are involved in disease’s pathophysiology." (PMID 33514397, 2021). "ApoE-deficient rat models generated by research labs and Envigo RMS (HsdSage:SD-ApoEem1Sage rat, Saint Louis, MO, USA) have been used in studies of atherogenic phenotypes and Alzheimer’s disease." (PMID 34361033, 2021). "Both analysis of specific SNPs in the APOE gene, and genetic risk scores do not suggest an increased risk for all family members of Alzheimer's disease." (PMID 33763108, 2021). "This recommendation is also conditional on any context-specific policies and regulations related to APOE genetic testing, as well as the patient's consent to undergo APOE testing and disclosure of the results related to Alzheimer's disease risk (or not)." (PMID 35237638, 2021). "The results presented here suggest hippocampal subfields have the potential to be important markers of known Alzheimer’s disease risk factors, in healthy individuals, when accounting for non-linear age effects and APOE and sex interactions." (PMID 33615215, 2021). "Of the cholesterol regulatory genes implicated in AMD, the cholesterol transporter APOE is especially enigmatic because humans are the only species that express APOE allelic variants, which show reversed risk associations between AMD and Alzheimer’s disease." (PMID 33822768, 2021). "Mechanisms underlying the protective effect of apolipoprotein E (APOE) ε2 against Alzheimer disease (AD) are not well understood." (PMID 34480088, 2021). "Our project hypothesis holds that the treatment scheme can be selected according to the APOE genotyping of Alzheimer’s disease." (PMID 34924994, 2021). "Apolipoprotein E (APOE) ε2 is a protective genetic factor for Alzheimer’s disease (AD)." (PMID 33994988, 2021). "One example of an apoE mimetic peptide designed for Alzheimer’s disease is CN-105 (Cerenova, LLC)." (PMID 33800446, 2021). "Keywords for this topic, such as tauopathies, Alzheimer’s disease, prion-like propagation, tau self-aggregation, endocytosis, neuron-glial communication, neuroinflammation, and apolipoprotein E were first chosen, and searches conducted in PubMed, Google Scholar, and Web of Science." (PMID 33672982, 2021). "We propose that this novel transcript may be a means of regulating APOE in a disease state or could itself be driven by Alzheimer’s disease pathology." (PMID 33824317, 2021). "Our findings imply that the APOE ε4 allele alters associations between circulating DHA and volumes of the entorhinal cortex and hippocampus in adults without dementia, almost a decade before the expected age of Alzheimer’s disease onset." (PMID 34007965, 2021). "The aim of this study was to investigate the association between various genetic predictors (APOE, AD PRS, and Aβ PRS), Aβ misfolding in blood plasma, a unique marker of Alzheimer associated neuropathological changes, and Alzheimer’s disease occurrence within 14 years." (PMID 33934115, 2021). "Most published studies used data form the Alzheimer's Disease Neuroimaging Initiative (ADNI) where the cohort consists of predominantly LOAD patients: APOE ε4 accelerated hippocampal atrophy in AD, however, there is not enough evidence for the relationship between APOE ε4 and cognitive decline." (PMID 34127075, 2021). "ApoE, present in the CNS and the periphery, represents a critical link between these two compartments and could influence Alzheimer’s disease (AD) pathogenesis by disrupting the blood–brain barrier (BBB) integrity from both sides." (PMID 33679311, 2021).
Alzheimer disease (continued). "It has been well established that apolipoprotein E (ApoE) is a very important genetic risk factor for age-dependent chronic diseases, including Alzheimer’s disease, but not all trials have controlled for this." (PMID 32846900, 2020). "One such predictor is well-known already: carriers of either one or two APOE e4 alleles (as opposed to no such alleles) are not just at higher risk of a diagnosis of Alzheimer’s disease, but also appear to be at risk of steeper cognitive decline." (PMID 30760887, 2020). "However, this questions model training in these studies, as APOE has been reported as affecting Alzheimer’s disease as early as 1993." (PMID 32351543, 2020). "For example with the prioritization of APOE by models for Alzheimer’s disease, it could also be argued that this validates the model performance, as this gene is expected to be prioritized." (PMID 32351543, 2020). "The objective of this study was to assess the association of sex and the apolipoprotein E (APOE) ε4 allele with brain tau deposition and atrophy in older adults with Alzheimer's disease (AD) using quantitative 18F-AV-1451 positron emission tomography (PET) and magnetic resonance imaging (MRI)." (PMID 32929366, 2020). "Many Alzheimer’s disease (AD) genes including Apolipoprotein E (APOE) are found to be expressed in blood-derived macrophages and thus may alter blood protein levels." (PMID 32427856, 2020). "Here, we tested STM performance in a large cohort of individuals (N = 1277); nine hundred and fifty-nine of which included carrier and non-carriers of the APOE ε4 gene, those at highest risk of developing Alzheimer’s disease." (PMID 32528115, 2020). "The relationship between the apolipoprotein E (APOE)-ε4 allele, triglyceride (TG) level, and cholesterol level and an increased risk of developing Alzheimer’s disease (AD) has been well established, but their relationship with behavioral-variant frontotemporal dementia (bvFTD) is not well-known." (PMID 33312717, 2020). "Here we examine the association between polygenic scores for Alzheimer’s disease both with and without the APOE region (chr19: 45,384,477 to 45,432,606, build 37/hg 19) at different P value thresholds and dementia." (PMID 33143703, 2020). "The ApoE e4 genotype is less frequent in the Indian population than in people of European ancestry, though there is increased frequency of occurrence in persons with Alzheimer's dementia and vascular dementia." (PMID 33192744, 2020). "This contrasts with findings from a previous study testing the consequences of an Alzheimer’s disease PRS without APOE, which only reported a significant association with NFTs and not β-amyloid plaques." (PMID 33376986, 2020). "The allele ε4 of the apolipoprotein E gene (APOE ε4) is the major genetic risk factor for non-dominantly inherited Alzheimer’s Disease (AD)." (PMID 32034174, 2020). "Moreover, binding of C1q to apoE has been suggested to reduce C1q-mediated activation of the classical pathway implicating that apoE, the major factor related to Alzheimer’s disease, acts as a complement inhibitor." (PMID 33363547, 2020). "This study aimed to investigate whether the midlife cognitive activity and physical activity moderate the relationship between apolipoprotein Eε4 (APOE4) and in vivo Alzheimer’s disease (AD) pathologies." (PMID 32256335, 2020). "In summary, our data indicate that APOE influences Alzheimer’s disease neuropathology via two independent pathways, one where β-amyloid accumulation correlates with the development of tauopathy (NFTs), and a second pathway with direct effects on NFTs independent of β-amyloidosis." (PMID 33376986, 2020). "The ε4 allele of the apolipoprotein E (APOE) gene and lower apolipoprotein E (apoE) protein levels in plasma are risk factors for Alzheimer disease, but the underlying biological mechanisms are not fully understood." (PMID 32648923, 2020).
Alzheimer disease (continued). "ApoE polymorphisms have gained attention in TBI due to their association with BBB breakdown in cases of deficiency or deletion, and correlation to late-onset Alzheimer’s disease (ApoE4)." (PMID 32397302, 2020). "APOE alleles have a major impact on aging-associated diseases, particularly cardiovascular disease (CVD), stroke, Parkinson’s, lewy body dementia, multiple sclerosis, and late-onset Alzheimer’s disease (AD)." (PMID 32587511, 2020). "A previous meta-analysis showed that these factors do not alter the influence of the APOE ε4 allele in dementia, whereas others have reported that the effects of statins on Alzheimer’s disease patients varied according to race." (PMID 32581766, 2020). "In addition, many genes closely related to neurological diseases, such as Got1, ApoE, Gm2a, have been found to interact with TET1 in OPCs; and Cst3 is associated with dementia in Lewy body disease and Alzheimer's Disease." (PMID 32974003, 2020). "Predictive performance over the model using APOE burden was improved by adding PHS when classifying CN versus MCI (AUC increase of 0.018) or by including PHS or PRS-cs when classifying CN versus MCI or Alzheimer’s disease (AUC increase of 0.011 or 0.02)." (PMID 32226939, 2020). "Peptide AEM-28 attenuates the effects of oxidative stress on ApoE secretion, inhibits amyloid plaque deposition, and thus could be beneficial in the treatment of Alzheimer’s disease." (PMID 32462055, 2020). "For instance, one study reported a PGS area under the curve of 0.57 for Alzheimer’s disease (parental proxy) using 21 SNPs and excluding the APOE region, while another study reported using more than 200,000 variants (including APOE) and a PGS area under the curve of 0.84 for Alzheimer’s disease." (PMID 33143703, 2020). "Associations of Alzheimer disease (AD) with haplotypes of TOMM40 and APOE were investigated." (PMID 32472747, 2020). "According to the Ensembl database, this SNP is located in the TOMM40 gene and in close proximity to the APOE gene but may also influence Alzheimer’s disease and age-related macular degeneration." (PMID 32471361, 2020). "Zinc and apolipoprotein E (apoE) are reportedly involved in the pathology of Alzheimer’s disease." (PMID 31991844, 2020). "In this study, we sought to characterize and compare the earliest longitudinal white matter differences between non-carriers and carriers of APOE ε4 allele, the major genetic risk factor for late-onset Alzheimer's disease." (PMID 32822813, 2020). "For one of the participants with young onset family history, the participant had an APOE ε4 allele present but negative autosomal dominant Alzheimer’s disease genetic testing, and the other participant had no allelic or genetic information available." (PMID 32671341, 2020). "Apolipoprotein E (APOE), which is believed to be associated with AD pathogenesis, has been reported to modulate the response to DNP treatment; ABCA1, which plays a key role in cholesterol transport and APOE metabolism in the brain, has been reported to be related to Alzheimer's disease." (PMID 32636753, 2020). "BIN1 is the most important risk locus for Late Onset Alzheimer’s Disease (LOAD), after ApoE." (PMID 31408457, 2019). "Among non-Hispanic white people, homozygous carriers of APOE ε4 exhibit up to a 12-fold higher risk of Alzheimer disease, but this same haplotype exerts little or no risk for black or Hispanic people." (PMID 30726504, 2019). "The association of anthocyanidins with Alzheimer’s dementia risk occurred only among those who were APOE-ɛ4 negative (Q4 vs. Q1: HR = 0.46, 95% CI = 0.29 to 0.73) and not in those without the allele (Q4 vs. Q1: HR = 1.5, 95% CI = 0.79 to 3.0)." (PMID 31847371, 2019). "For example, Watson was one of the first people to have his genome sequenced and chose to have his APOE information redacted (as he preferred not to know if he had an APOE genotype associated with an increased chance of developing Alzheimer’s disease)." (PMID 31281738, 2019).
Alzheimer disease (continued). "However, the prevalence of APOE*4 among individuals with Alzheimer disease is reportedly lower in Asian countries than in North America and Northern Europe." (PMID 31335910, 2019). "Blood-based β-amyloid 42 and β-amyloid 40 ratio together with APOE genotype may be used as prescreening tests in primary care and in clinical Alzheimer disease trials to lower the costs and number of positron emission tomography scans and lumbar punctures." (PMID 31233127, 2019). "Although most cases of Alzheimer's disease are not directly heritable, genetic risk factors have been identified, the strongest of which is the epsilon 4 isoform of apolipoprotein E (APOE4)." (PMID 31853523, 2019). "Apolipoprotein E (apoE) is the key regulator of plasma lipids, mediating altered functionalities in lipoprotein metabolism – affecting the risk of coronary artery (CAD) and Alzheimer’s diseases, as well as longevity." (PMID 30679475, 2019). "Genetic variants in PICALM, BIN1, CD2AP, and RIN3 are associated with increased risk of Alzheimer’s disease, all dementia, and suggested vascular dementia independent of the strong APOE ε4 allele." (PMID 30830563, 2019). "Late-Onset Alzheimer’s Disease is a complex multifactorial disease; thus, the APOE variants do not give a definite prediction of the disease by themselves." (PMID 31842725, 2019). "In this study we examined whether sex modulates the ApoE ε4 effect on brain tau deposition measured by 18F-AV-1451 PET among MCI subjects in the Alzheimer's Disease Neuroimaging Initiative (ADNI)." (PMID 31410194, 2019). "APOE apolipoprotein plays a key role in maintaining cerebral phospholipid homeostasis and plays a vital role in the pathogenesis and pathology of Alzheimer’s disease (AD)." (PMID 31481902, 2019). "While some studies report better performance on particular cognitive tests among carriers, higher scores are not expected, given the association between APOE*4 and Alzheimer disease." (PMID 31335910, 2019). "•There are three apolipoprotein E isoforms, and E4E4 increases the risk for Alzheimer's disease." (PMID 31051176, 2019). "Most genetic research on late-onset Alzheimer’s disease (LOAD) has focused on genome-wide association studies (GWAS) that have provided low effect size results in general, with the exception of apolipoprotein E (ApoE)." (PMID 30646578, 2019). "For example, 23andMe conducts an APOE genetic test in relation to Alzheimer disease." (PMID 31610629, 2019). "Firstly, all of the analyses we present here are associations or correlations than can only imply a link between APOE-ε4 status, hyperconnectivity and future risk of developing Alzheimer’s disease – no causal relationships can be proved in this type of study." (PMID 31038453, 2019). "In this study, we tested the prediction accuracy of AD, mild cognitive impairment (MCI), and amyloid deposition risks with PRS, including and excluding APOE genotypes in a large publicly available dataset with extensive phenotypic data, the Alzheimer's Disease Neuroimaging Initiative cohort." (PMID 31199530, 2019). "As examples of protein biomarkers, they proposed the detection of HIgG at ng/mL levels, anti-hepatitis B antibodies at levels low enough for assuring the efficiency of vaccination (3 mIU/mL) and Alzheimer’s disease biomarkers (ApoE and beta amyloid) at diagnostically relevant levels." (PMID 31771201, 2019). "Apolipoprotein E (apoE) plays an essential role in lipid metabolism, and variability in this protein influences several lipid-related diseases of older age, including coronary heart disease, stroke, and Alzheimer’s disease (AD)." (PMID 29739406, 2018). "The apoE ε4 allele was associated not only with higher serum TC and LDL-C levels but also with higher oxidative stress, a more pro-inflammatory state and increased risk of cardiovascular disease and late-onset Alzheimer’s disease." (PMID 29636060, 2018).
Alzheimer disease (continued). "In addition to altered ApoE levels, patients with Alzheimer’s disease have increased ferritin levels in their cerebrospinal fluid (CSF), a marker of brain iron content." (PMID 30360386, 2018). "In addition, 21 participants were identified to be heterozygous or homozygous for the APOE (MIM: 107741) e4 allele, which is associated with increased lifetime risk for developing Alzheimer's disease (MIM: 104310)." (PMID 30487145, 2018). "In particular, FERRITIN levels in cerebrospinal fluid (an indicator of iron storage capacity) are very significantly higher in carriers of the major LOsAD risk allele, the ε4 allele of the gene APOE (APOE4), and predict conversion from mild cognitive impairment (MCI) to Alzheimer’s disease." (PMID 30150923, 2018). "However, another possibility is that individuals with both risk factors were further along the Alzheimer's disease continuum, given the younger age of onset of Alzheimer's disease in patients with ApoE ε4 genotype." (PMID 29527500, 2018). "There is some evidence that APOE is associated with age-related cognitive decline that is not attributable to Alzheimer’s disease." (PMID 30339707, 2018). "Similar to other similar studies, we were not able to rule out the possibility that pre-clinical Alzheimer’s disease was responsible for the association between APOE and cognitive change." (PMID 30339707, 2018). "Amyloid-β and the combination of ApoE ε4 led to less extensive elevated metabolic correlations compared to other normal older adults, as well as a metabolic brain network more similar to youth and Alzheimer's disease." (PMID 29527500, 2018). "While the Risk Evaluation and Education for Alzheimer’s Disease (REVEAL) study demonstrated that APOE ε4 disclosure to adult children of AD patients did not result in significant short-term psychological effects, the long-term effects have not been evaluated." (PMID 30011822, 2018). "Finally, in addition to its implication in lipoprotein metabolism and cardiovascular disease, ApoE exerts pleiotropic roles in Alzheimer's disease, immunoregulation and cognition." (PMID 30305304, 2018). "Compared to persons without the APOE ε4 variant, those with two copies of the ε4 variant are known to have more than a sevenfold elevated risk of developing Alzheimer's disease, the 6th leading cause of mortality in the United States." (PMID 29770230, 2018). "Disruption is more exaggerated in patients with Alzheimer's disease and in ApoE ε4 carriers." (PMID 29527500, 2018). "It is already known that the onset of Alzheimer's disease (AD) is related to the APOE gene, and the present results indicate that this gene is also a risk factor for the onset of PDD, suggesting that the pathogeneses of PDD and AD may be similar." (PMID 30405900, 2018). "The ε4 allele of Apolipoprotein E (APOE) is the strongest known genetic risk factor of Alzheimer’s disease (AD) but does not account for the entirety of genetic risk." (PMID 30143603, 2018). "Other genes, ApoE and MAPT, are of particular interest because of their known association with dementia in other neurodegenerative diseases, such as Alzheimer's disease (AD) and atypical parkinsonian syndromes, including progressive supranuclear palsy and corticobasal degeneration." (PMID 30155299, 2018). "Here, to address the role of APOE haplotypes, we reassessed the diversity of APOE locus in major ethnic groups and in Alzheimer’s Disease Neuroimaging Initiative (ADNI) dataset on patients with AD, and subjects with mild cognitive impairment (MCI), and control non-demented individuals." (PMID 29745836, 2018). "Here we performed a gene-based association analysis of rare variants within genes in the vicinity of APOE with cerebrospinal fluid (CSF) and LOAD-related neuroimaging markers using a WGS data set (N = 757) from the Alzheimer’s Disease Neuroimaging Initiative (ADNI) cohort." (PMID 28589856, 2017).